IFNE (interferon epsilon)
Diseases named in the same sentence as IFNE in open-access papers (continued):
Sharing a sentence is not in itself a finding about the gene and the disease.
infection (23 papers, 2013 to 2026). The state of being infected such as from the introduction of a foreign agent such as serum, vaccine, antigenic substance or organism. "H322 cells have a homozygous deletion in a region of chromosome 9 encoding IFNαgenes, IFNβ1, IFNω1, and IFNε genes, leading to downregulation of immune response and high infection rates." (PMID 40434103, 2025). "Here, we demonstrate that IFNε deficiency leads to a reduction in NK cell numbers that is associated with increased infection and upper RT pathology." (PMID 38263527, 2024). "We next compared the effects of IL-15 and NK cell deficiency to those of IFNε deficiency and determined if IL-15 and NK cells are required for IFNε-mediated protection against infection." (PMID 38263527, 2024). "We show that rIFNε and rIL-15 have similar effects on NK cell accumulation during infection in WT mice, consistent with IFNε mediating this NK cell response through the actions of IL-15 in vivo." (PMID 38263527, 2024). "To determine if IFNε is involved in the recruitment of immune cells to the FRT during the early stages of infection, we performed flow cytometry to quantify common leukocyte populations in uterine tissues from Chlamydia-infected WT and Ifne-/- mice." (PMID 38263527, 2024). "Both prophylactic and therapeutic IFNε treatment induced a strong interferon-driven anti-viral response 24 hours post-infection." (PMID 39621805, 2024). "We also show the mechanisms by which IFNε primes for NK cell responses to infection are through driving the accumulation of NK cell progenitors and the expression of IL-15 in the uterus and by directly stimulating NK cell activation." (PMID 38263527, 2024). "We also used NK cell deficient Il15-/- mice and rIFNε to show that NK cells are the major contributors to IFNε-mediated infection control in vivo." (PMID 38263527, 2024). "Pre-treatment with IFNs imparted a strong block to infection whereas treatment at 3 hpi was less effective and antiviral effects were almost lost when treatment was delayed until 24 hpi for both IFNε and IFNα." (PMID 36897927, 2023). "This protection was most significant during the early stages of infection as indicated by the high levels of infectious virus recovered in the VW of IFNε-/- mice that closely mirrored levels observed in the highly susceptible IFNAR1-/- mice." (PMID 36897927, 2023). "Here we have shown modulation of IFNε levels in the LFRT can alter the infectivity of mice by ZIKV intravaginal infection." (PMID 36897927, 2023). "At five days post-infection, our results indicated that IFNε treatment significantly decreased extracellular viral release in VK2E6E7 cells." (PMID 36014974, 2022). "Unfortunately, there is a huge gap in knowledge as to how IFNε-mediated signaling responds to infections from other globally relevant viruses, especially flaviviruses." (PMID 36014974, 2022). "We also performed the PrestoBlue assay to analyze the potential effects of IFNε signaling in VK2 cells during infection." (PMID 36014974, 2022). "For three values of kSTATP,IFNe, we show the plaque size and shape at 80 hours post-infection and the cell type dynamics over time." (PMID 34695114, 2021). "To confirm the role of IFNε in inducing IL-15 and NK cell responses, we then performed gain-of-function studies in WT mice by transcervical and intravaginal administration of rIFNε prior to infection (Fig. EV4A,B)." (PMID 38263527, 2024). "Thus, Il15-/- mice are the most appropriate tool available to determine if there are NK cell-independent effects of IFNε on infection and protective responses." (PMID 38263527, 2024). "We also previously found that IFNε has direct effects on infection in epithelial cells." (PMID 38263527, 2024). "These IFNε-mediated effects on NK cells are important in protecting against infection." (PMID 38263527, 2024).
infection (continued). "IFNɛ activated STAT1/2 pathways similar to IFNα and λ that were inhibited by ZIKV-encoded non-structural (NS) proteins, but not if IFNε exposure preceded infection." (PMID 36897927, 2023). "Antibody mediated neutralisation of IFNε in WT mice significantly increased infection." (PMID 36897927, 2023). "Mock and chlamydia-infected ERαKO mice also expressed more IFNε early during infection." (PMID 36636722, 2022). "Thus, collectively, these findings show that IFNε has important roles in protecting the FRT from infection and associated pathology, largely by increasing NK cell responses, in addition to directly suppressing infection in epithelial cells." (PMID 38263527, 2024). "However, we show that IFNε does increase the numbers of NK cells systemically during infection." (PMID 38263527, 2024). "Unlike the vagina and ectocervix, in which IFNε is expressed in the basal and parabasal layers of the epithelium, IFNε is also detected in the surface of the endometrial luminal epithelium, suggesting that IFNε may play a role in immune protection from infection in the endometrium." (PMID 36358904, 2022). "This study is the first to identify a crucial role for the constitutive expression of a uterine-specific factor, IFNε, in controlling NK cell responses in the uterus and protecting against FRT infections." (PMID 38263527, 2024). "We propose the lower specific activity of IFNε provides an evolutionary advantage because of its constitutive presence in the FRT, striking a balance between limiting infection, inflammation, and normal reproductive function in these tissues." (PMID 36897927, 2023). "Importantly, IFNε is the only IFN known to be produced constitutively by mucosal surfaces of the non-pregnant FRT suggesting it may have a significant impact on human FRT infections." (PMID 36897927, 2023). "The hormonal environment also altered T cell recruitment and IFNε production the genital tracts of infected OVT and Sham mice on day 10 post infection." (PMID 36636722, 2022). "Both prophylactic and therapeutic IFNε treatment reduced the expression of inflammatory marker gene sets at 24 hours post-infection, although this reduction did not achieve statistical significance." (PMID 39621805, 2024). "Treatment does not significantly affect pre-pro-like NK cell numbers in the uterus during infection and does not change Ifne expression, demonstrating that IL-15 is incapable of driving IFNε expression and acts downstream." (PMID 38263527, 2024). "We next examined whether these IFNε-mediated effects on NK cell number, activity, and IFNγ production are specific to the FRT or are also systemic, both at baseline and during infection." (PMID 38263527, 2024). "Similar to previous reports, we found detectable levels of IFNε mRNA in the brain of WT mice, and in the absence of IFNε, mice displayed greater levels of infection in the brain by 5 dpi." (PMID 36897927, 2023). "The constitutive presence of IFNε in the non-pregnant FRT is likely significant in human infections as ZIKV can effectively evade post-infection IFN responses but is strongly inhibited by prophylactic treatment." (PMID 36897927, 2023). "The amniotic fluid concentration of IFNε is elevated in women undergoing spontaneous preterm labor with intra-amniotic infection than in women with no infection or sterile intra-amniotic inflammation." (PMID 36358904, 2022). "Although we did not observe hormonal regulation in the lower hFRT, IFNE expression has been previously demonstrated to be upregulated in the human ectocervix upon exposure to semen and has been hypothesized to have an immunomodulatory mechanism within the hFRT to reduce risk of infection by HIV." (PMID 35862222, 2022). "However, stimulation of Sertoli cells with exogenous IFNε in the absence of infection produced an earlier potent ISG response at 12 hours post-treatment." (PMID 39621805, 2024).
infection (continued). "Our data show that IFNε is constitutively expressed in murine and human testicular macrophages, Leydig cells and meiotic and post-meiotic spermatogenic cells, in the absence of infection." (PMID 39621805, 2024). "Interferon epsilon (IFNε) is a unique type I IFN that, unlike other family members, is not induced by infection but is constitutively expressed in epithelial tissues." (PMID 42084361, 2026). "Although DMPA treated WT mice expressed low levels of IFNε, we found that its presence in the FRT was sufficient to offer significant protection against ZIKV iVag infection compared to mice lacking IFNε entirely." (PMID 36897927, 2023). "Upon in vitro infection with ZIKVBR, a marked induction of mRNA expression of IFNB1, IFNL1, IFNL2 and IFNL3 genes but not of IFNE was observed." (PMID 32745093, 2020). "This indicates that IFNε is critical in potentiating protective innate immune responses in the FRT, however, how it affects immune responses and the mechanisms by which it mediates defense against infection are not yet known." (PMID 38263527, 2024).
tumor (11 papers, 2019 to 2026). "An in vivo competition assay of these alleles identified that loss of interferon epsilon (Ifne) was a tumor-specific driver of these phenotypes in pancreas cancer." (PMID 38326496, 2024). "Interferon‐ε (IFNε), an intrinsic tumor suppressor lost during ovarian cancer development, exerts anti‐tumor effects by directly targeting tumor cells and activating anti‐tumor immunity." (PMID 40968783, 2026). "IFN type I (IFNα, IFNβ, IFNω, IFNε, and IFNк) has multiple anti-tumour activities, such as direct tumour cell killing and the stimulation of immune cells including DCs and CD8+ T cells." (PMID 37691915, 2023). "Most notably, IFNE exerts a tumor-suppressive role in BE, but not in EAC, by reducing IFN response and inducing a cold immune microenvironment." (PMID 39753721, 2025). "Mechanistically, IFN co-deletion disrupted type I IFN signaling in the tumor microenvironment, leading to marked changes in infiltrating immune cells and escape from CD8+ T-cell surveillance, effects largely driven by the poorly understood interferon epsilon." (PMID 36344707, 2022).
bacterial infections (6 papers, 2014 to 2022). "Data showed that females exhibit higher levels of anti-viral type 1 interferons IFNA17, IFNA2, IFIT1, IFIT3 and IFNE in the immune tissues/cells, which serve as the first line of defense against viral and bacterial infections." (PMID 33271804, 2020). "For example, the uterus expresses higher levels of interferon epsilon, which protects against viral and bacterial infections, while the cervix, vagina and ovary express lower levels." (PMID 24994117, 2014). "IFNE may protect the female reproductive tract from viral and bacterial infection." (PMID 31080783, 2019).
cancer (6 papers, 2017 to 2022). A tumor composed of atypical neoplastic, often pleomorphic cells that invade other tissues. "The results of this study contribute towards the importance of discovering and characterizing IFNε from this unique Arabian camel, and propose its potential use for the treatment of cancer." (PMID 31490936, 2019). "Cytotoxicity and apoptosis assays were then performed to define the effect of the purified recombinant IFNε protein on human cancer cell lines." (PMID 31490936, 2019). "Three genes were located between these two lncRNA genes: IFNE, MTAP, and CDKN2A, all of which are associated with cancer." (PMID 27903974, 2017). "Through the analysis of copy number alteration of PM samples, we found that there were significant deletions in many genomic regions of PM samples, involving many cancer genes and immune related genes (such as B2M, RHOA, IFNE, JAK1/2, etc.)." (PMID 31570735, 2019). "In addition, three interferons (IFNA1, IFNA2, and IFNE) and MIR31HG (microRNA-31 Host Gene) were also in the top 10 for these two cancers." (PMID 32033319, 2020).
IFNE also shares sentences with these, for which no sentence is quoted: HIV-1 infection (2 papers); human papilloma virus infection (2); asthma (1); bladder cancer (1); cervical squamous intraepithelial lesion (1); condyloma acuminatum (1); glioma (1); infertile (1); ischemic stroke (1); laryngeal papilloma (1); lung carcinoma (1); orchitis (1); pancreatic cancers (1); Pneumovirus Infections (1); Stroke (1); verruca vulgaris (1); viral diseases (1); vitiligo (1).